LHPP (phospholysine phosphohistidine inorganic pyrophosphate phosphatase)
Diseases named in the same sentence as LHPP in open-access papers (continued):
Sharing a sentence is not in itself a finding about the gene and the disease.
tumor (continued). "In most tumor types, there was no clear association between LHPP expression and pathological stage." (PMID 36376886, 2022). "Therefore, we supposed that LHPP might serve as a tumor suppressor by downregulating the phosphorylation of oncogenes during the progression of most cancers." (PMID 36376886, 2022). "Interestingly, we found that LHPP protein levels were obviously attenuated at the initial stage of tumor development, which suggested that LHPP protein might play an important role in maintaining the development of normal tissues." (PMID 36376886, 2022). "Thus, LHPP exerts a tumour suppressor effect through acetylation." (PMID 35568711, 2022). "Therefore, we investigated the potential correlation between LHPP gene expression and the infiltration level of tumor fibroblasts in multiple cancer types from the TCGA project by using the TIMER, CIBERSORT, CIBERSORT-ABS, TIDE, XCELL, MCPCOUNTER, QUANTISEQ and EPIC algorithms." (PMID 36376886, 2022). "From our perspective, LHPP may exert its anti-tumor effects through multiple signaling pathways." (PMID 36484014, 2022). "In addition, forced expression of LHPP significantly inhibited tumor volume as well as weight." (PMID 33426063, 2020). "Compared to the control group, LHPP-overexpressing AGS GC cells showed a statistically significant reduction in the tumor formation rate and number, as well as a decrease in tumor weight and volume." (PMID 40240758, 2025). "In LGG, pathways associated with a good prognosis include oxidative phosphorylation (LHPP, PPA1, CYC1), supported by a high WWOX/HIF1A ratio, which improves energy metabolism and reduces tumour aggressiveness." (PMID 41007296, 2025). "Oxidative phosphorylation components (NDFs, COXs, TCIRG1, LHPP) and chemical carcinogenesis pathways involving reactive oxygen species (CYP1B1, GSTs, AKT2, IKBKB, MAPK3, MAP2K2) exacerbate DNA damage and promote tumour aggressiveness." (PMID 41007296, 2025). "Analyses of MeRIP-seq, mRNA-seq, and databases have identified LHPP and NKX3–1 as the main targets of YTHDF2, and both LHPP and NKX3–1 are tumor suppressors that regulate tumor progression by inhibiting AKT phosphorylation." (PMID 38166703, 2024). "Conversely, the downregulation of LHPP, HMOX1, and BCL2 disrupt tumor-suppressive functions, oxidative stress management, and apoptotic processes, respectively." (PMID 39468431, 2024). "Their representative genes include the tumor suppressor genes LHPP, VGLL4, USP53, and CLDN6, which have been reported to play significant anti-tumor functions in a variety of cancer types." (PMID 38831454, 2024). "Overexpressing LHPP protein not only inhibited CRC cells migration and invasion in vitro but also repressed tumor metastasis in vivo." (PMID 34608127, 2021). "In conclusion, both LHPP and NKX3–1 are tumor suppressors to inhibit AKT phosphorylation in PCa progressions." (PMID 33121495, 2020). "LHPP functions as a tumor suppressor gene in GC by regulating the PI3K/AKT/mTOR pathway and inhibiting the Wnt/β-catenin signaling pathway, the TGFβ/Smad signaling pathway, AKT phosphorylation, and other mechanisms to suppress tumor occurrence and progression." (PMID 40240758, 2025). "LHPP has been suggested to play a tumor suppressor role in various cancers, while the molecular mechanism identified in most subsequent studies was attributed to the AKT-pSer pathway, which regulates tumor cell proliferation, metastasis, and apoptosis." (PMID 40988976, 2025). "LHPP is a tumor suppressor gene originally identified in HCC and later in many other tumor types." (PMID 38696452, 2024). "This activation also impairs the function of natural killer cells, enhancing the ability of tumor cells to evade the immune system while circulating.Among the genes governed by TFs, LHPP, also known as phospholysine phosphohistidine inorganic pyrophosphate phosphatase." (PMID 39468431, 2024).
tumor (continued). "Further investigation verified that YTHDF2 could recognize the abundance of m6A-modified mRNA of LHPP and NKX3-1 induced by METTL3 and degrade them, thereby promoting AKT phosphorylation and tumour progression." (PMID 37284313, 2023). "In particular, the comparison result of LHPP expression in paired-sample analysis further demonstrated that LHPP is definitely down-regulated in tumor than in the matched noncancerous samples (p < 0.05)." (PMID 36484014, 2022). "Hou revealed the unknown mechanism of LHPP as a tumor suppressor in CRC metastasis, where E-cadherin was significantly increased with LHPP overexpression." (PMID 36551152, 2022). "Tumor suppressors NKX3.1 and LHPP were the precise targets of METTL3 and YTHDF2." (PMID 34899855, 2021). "And the results indicated that knock-down of NKX3–1 and LHPP could significantly induced the tumor growth, but knock down of YTHDF2 or METTL3 partially rescued the mice tumor growth induced by knock down of LHPP and NKX3–1." (PMID 33121495, 2020). "The expression level of LHPP was lower in PDAC tumor tissues than in adjacent nontumor controls." (PMID 40619414, 2025).
cancer (20 papers, 2020 to 2025). A tumor composed of atypical neoplastic, often pleomorphic cells that invade other tissues. "LHPP was found to be down-regulated and associated with cancer progression and favorable prognosis in many cancers 7-9." (PMID 36484014, 2022). "Interestingly, we discovered that LHPP gene expression was positively associated with the infiltration value of cancer-associated fibroblasts in HNSC, STAD and TGCT." (PMID 36376886, 2022). "Furthermore, the histidine phosphatase LHPP has been found to be associated with cancer." (PMID 32186702, 2020). "LHPP is a cancer suppressor, and its content is negatively correlated with the incidence of many types of cancer." (PMID 40731003, 2025). "Another mechanism by which LHPP inhibits metastasis is by downregulating the AKT pathway in various cancers, thus decreasing cell proliferation, migration, and invasion." (PMID 39063217, 2024). "To elucidate the clinical implications of LHPP, we initially analyzed the TCGA database to examine LHPP expression patterns across various human cancers." (PMID 39261475, 2024). "Researchers have observed that LHPP plays a crucial role in inhibiting proliferation, growth, migration, invasion, and cell metabolism across various cancers." (PMID 38292328, 2024). "Despite being relatively understudied, histidine phosphatases, particularly LHPP, are gaining recognition for their potential role in cancer progression." (PMID 39261475, 2024). "Primarily, we evaluated the expression levels of the LHPP gene among all 33 cancer types in the TCGA database." (PMID 36376886, 2022). "For the past few years, a lot of evidence has illustrated that LHPP is closely interrelated to the development of cancer." (PMID 35002505, 2022). "Since this observation, LHPP has been found to play a role in a wide range of cancers, with the suggestion that its function is to inhibit the PI3 kinase / protein kinase B (AKT) signaling pathway." (PMID 36048825, 2022). "Our research primarily uncovered the expression profile of LHPP across 33 cancer types using TCGA, GTEX and GEO databases." (PMID 36376886, 2022). "Cancer cases were divided into two groups according to the performance status of LHPP gene expression, namely, the high-expression group and the low-expression group." (PMID 36376886, 2022). "First, a greater number of pathological specimens should be collected to examine LHPP expression between normal and cancer tissues." (PMID 36376886, 2022). "Mechanistically, LHPP suppresses cancer cell proliferation, metastasis, and energy metabolism and promote cell apoptosis and autophagy." (PMID 36376886, 2022). "Although emerging evidence has revealed that LHPP, a histidine phosphatase protein, suppresses the progression of different cancers, a pan-cancer analysis still remains unavailable." (PMID 36376886, 2022). "Consistently, our results demonstrated that LHPP expression in normal tissues was definitely higher than that in cancer tissues." (PMID 36376886, 2022). "Second, other cell lines from different cancer types should be used to define the biological functions of LHPP protein." (PMID 36376886, 2022). "We performed Western blot assays and immunohistochemistry to explore LHPP expression in normal tissues and cancer tissues (n = 20)." (PMID 36376886, 2022). "Difference analysis showed abnormal expression of mRNA, including down-regulated expression of LHPP in cancer." (PMID 35002505, 2022). "At present, LHPP has been rarely studied, and LHPP has been scarcely evidenced to act as phosphatase in the development of carcinoma." (PMID 35002505, 2022). "Compared with adjacent tissues, LHPP protein levels in cancer tissues were significantly decreased (P < .05)." (PMID 31693242, 2020). "Evidence suggests that LHPP may play a role in mitotic catastrophe, an inherent mechanism for suppressing cancer formation." (PMID 39063217, 2024).
cancer (continued). "Numerous research elucidated that LHPP promoted apoptosis and inhibited proliferation in various types of cancer by reducing phosphorylated ATK expression and regulating AKT‐related signaling pathways, such as PI3K/AKT, PTEN/AKT, and ATK/AMPK signaling pathways." (PMID 38292328, 2024). "In the present study, we found the LHPP expression was lower in GC than in adjacent normal tissues as indicated by online databases such as The Cancer Genome Atlas Program (TCGA) and Gene Expression Omnibus (GEO) databases, along with samples from 90 GC patients." (PMID 38292328, 2024). "However, the precise molecular mechanism by which LHPP functions as a metastasis suppressor via its histidine phosphatase activity in cancer remains unexplored." (PMID 39063217, 2024). "In contrast, LHPP overexpression decreased these activities, suggesting that LHPP may play a role in inhibiting cancer progression." (PMID 39261475, 2024). "Recent explorations have highlighted the crucial role of LHPP in modulating cancer progression." (PMID 39261475, 2024). "As shown, the LHPP expression was lower in cancer tissues than that in normal oral mucosa tissue." (PMID 35002505, 2022). "In addition to the expression results, we also analyzed the survival status, genetic alteration, immune infiltration of LHPP in multiple human cancers." (PMID 36376886, 2022). "Based on these results and references, we hypothesized that LHPP might be involved in the development of pancancer and play a common role in the progression of different cancer types." (PMID 36376886, 2022). "As expected, LHPP expression was clearly higher in normal STAD tissues than in cancer tissues." (PMID 36376886, 2022). "Consequently, LHPP mRNA and protein expression were down-regulated in the most cancer tissues corresponding to normal tissues." (PMID 36376886, 2022). "Therefore, in this study, the genetic pattern of the LHPP gene was further analyzed in different cancer types from the TCGA project." (PMID 36376886, 2022). "Interestingly, LHPP dysregulation was commonly observed in many cancer types, as LHPP has common characteristics in cancer development." (PMID 34608127, 2021). "Furthermore, a specific inhibitor of Smad3 phosphorylation (SIS3) was applied to verify that LHPP repressed EMT of cancer cells by attenuating TGF-β/Smad signaling." (PMID 34608127, 2021). "Thus, the next study will focus on the further mechanism of LHPP biological functions during different cancer stages." (PMID 34608127, 2021). "LHPP expression was lower in cancer tissues than that in normal pancreatic tissue." (PMID 32186702, 2020). "Consequently, LHPP presents as a promising target in cancer therapy." (PMID 39261475, 2024). "Therefore, the role of LHPP could vary depending on tissue type and cellular context, potentially holding significant relevance in cancer progression." (PMID 39063217, 2024). "However, LHPP expression in cancer tissues was apparently increased in DLBC, LAML, OV and THYM." (PMID 36376886, 2022). "Moreover, stable cancer cell lines with LHPP overexpression or knockdown were established." (PMID 36484014, 2022). "In addition, a reduction in LHPP expression was observed in different cancer types." (PMID 36376886, 2022). "Numerous studies have reported that LHPP can inhibit cell metastasis and EMT progression in various types of cancer cells." (PMID 32904557, 2020). "To validate our findings, we recruited a cohort of 21 cancer patients for histological confirmation, revealing significant mRNA upregulation of STAT3, IL6, MMP9, MMP3, TGFB1, VEGF and HIF1A, coupled with downregulation of LHPP and PCK1, PTEN and BLC2." (PMID 39468431, 2024). "Colons of 1.5-year-old Lhpp−/− mice clearly displayed the deletion of LHPP, as shown by LHPP IHC staining, but no signs of cancer and/or inflammation." (PMID 37626656, 2023). "LHPP deregulated AKT and mTOR phosphorylation to repress cell proliferation and progression in colorectal, cervical, bladder and thyroid cancers." (PMID 36376886, 2022).
cancer (continued). "KEGG analysis of LHPP and NKX3–1 common negatively correlated genes also indicated that the most significant pathways including PI3K-AKT signaling pathway and several crucial pathways like ‘pathways in cancer’ and etc. were involved." (PMID 33121495, 2020). "Although the clinical prognosis of most cancer types was not correlated with LHPP expression levels after bioinformatics analysis, the clinical data from other references, including data on BLCA, LIHC, PAAD, CHOL and COAD provide markedly positive pathological maps with high LHPP performance." (PMID 36376886, 2022). "Furthermore, the expression of the LHPP gene was suppressed in STAD and COAD cancer tissues." (PMID 36376886, 2022). "Therefore, LHPP may regulate PaCa cell progression via the AKT signaling pathway, which plays an important role in the proliferation, migration, invasion, and apoptosis of cancer cells." (PMID 32186702, 2020). "The absence of LHPP, which leads to amplified AKT activity, is a distinctive feature of the aberrant PI3K/AKT signaling pathway in the genesis and progression of cancer." (PMID 39261475, 2024). "As shown, compared with normal oral mucosa tissue the LHPP expression was lower in cancer tissues, IHC staining also indicated LHPP expression is closely related to OSCC differentiation, suggesting that LHPP might play a negative role in OSCC tumorigenesis and function as a tumor suppressor gene." (PMID 35002505, 2022).
infection (1 paper, 2021). The state of being infected such as from the introduction of a foreign agent such as serum, vaccine, antigenic substance or organism. "Colony formation experiments further confirmed that the clonogenic capacity of both DOX-induced A2Lox-Cre mESCs and R1 mESCs overexpressing LHPP by lentiviral infection was significantly reduced." (PMID 33796530, 2021).
LHPP also shares sentences with these, for which no sentence is quoted: intrahepatic cholangiocarcinoma (2 papers); Oral Squamous Cell Carcinoma (2); acute myeloid leukemia (1); Alzheimer disease (1); asthma (1); bladder urothelial carcinoma (1); colon adenocarcinoma (1); colon cancer (1); Crohn disease (1); diffuse large B-cell lymphoma (1); hematological cancers (1); kidney chromophobe (1); leukemia (1); lymphoid neoplasm (1); neurological diseases (1); non-small cell lung carcinoma (1); ovarian cystadenocarcinoma (1); papillary thyroid cancer (1); paraganglioma (1); pharyngeal cancer (1); pheochromocytoma and (1); prostate adenocarcinoma (1); rectal cancer (1); renal carcinoma (1); testicular germ cell tumor (1); thymoma (1); thyroid cancer (1); thyroid disorders (1); ulcerative colitis (1); uterine carcinosarcoma (1).
A further 1 disease shares a sentence with LHPP in 1 paper.